AKR1B10 (aldo-keto reductase family 1 member B10)
Diseases named in the same sentence as AKR1B10 in open-access papers (continued):
Sharing a sentence is not in itself a finding about the gene and the disease.
tumor (continued). "By contrast, the downregulation of AKR1B10 in tumor cells suppresses the growth and progression of tumor." (PMID 34552036, 2021). "In high-grade tumors, we observed significantly decreased ratios of AKR1B10 mRNA levels in tumor tissues versus adjacent control tissues." (PMID 34298614, 2021). "Compared with para-tumor tissues, the levels of AKR1B10 in GC tissues were decreased in a significantly way." (PMID 34552036, 2021). "The results of the Oncomine platform showed that, compared to non-tumor tissues, AKR1B10 mRNA levels in GC tissues were increased in Cui and DErrico datasets." (PMID 34552036, 2021). "In summary, AKR1B10 is considered as a tumor suppressor in GC and is a promising therapeutic target." (PMID 34552036, 2021). "Our study showed that in GC, inhibition of the expression level of AKR1B10 modestly promoted the capacity of tumor to proliferate, migrate and form colony." (PMID 34552036, 2021). "In vivo experiment, knockdown of AKR1B10 promoted the growth of tumor, increased Vimentin, and E-cadherin significantly." (PMID 34552036, 2021). "The study was further support by the expression of AKR1B10 protein, which was reported to promote cell proliferation, growth and induces drug resistance to anti-tumour agents." (PMID 33670440, 2021). "In the second published study, we examined the ratio of AKR1B1 and AKR1B10 mRNA levels in tumor tissues versus adjacent control tissues in relation to the clinicopathological data of 51 patients." (PMID 34298614, 2021). "Studies revealed the involvement of AKR1B10 in the development and carcinogenesis of some tumors through effects on tumor cell growth and survival." (PMID 34521883, 2021). "The role of AKR1B10 in CRC tumor growth was analyzed by establishing an in vivo xenograft model using wild-type and AKR1B10-KD HT29 cells." (PMID 32615540, 2020). "Taken together, AKR1B10 acts as a tumor suppressor in CRC, and its ectopic expression promotes the growth of CRC cells in vitro." (PMID 32615540, 2020). "We found that reduced levels of AKR1B10 in the tumor tissues correlated significantly with advanced stages, greater invasiveness, increased tumor differentiation and poor survival of CRC patients, indicating that AKR1B10 is a potential tumor suppressor in CRC." (PMID 32615540, 2020). "In conclusion, AKR1B10 acts as a tumor suppressor in CRC by inactivating FGF1, and is a novel target for combination therapy of CRC." (PMID 32615540, 2020). "The AKR1B10 gene expression was substantially higher in the specimen collected from the tumor compared to the healthy lung tissue in the same patients." (PMID 32097409, 2020). "Together these data support a model in which AKR1B10 functions to maintain FAO in tumour cells, particularly during metastatic colonisation of the pro-oxidative lung microenvironment." (PMID 31221959, 2019). "Using hash and survival packages in R program, we performed Kaplan-Meier analysis of AKR1B10 and OS in HCC patients, which showed that AKR1B10 overexpression in tumor tissues was significantly associated with poor OS in HCC patients (log rank P = 0.004)." (PMID 31598161, 2019). "A number of experimental studies have shown that silencing of AKR1B10 prevents tumor growth and metastasis and induces cell death." (PMID 30959792, 2019). "The oncogenetic functions of AKR1B10 in HCC tumor growth were validated in HCC cell lines SMMC-7721, HepG2 and Hep3B." (PMID 31598161, 2019). "On another note, the relation between AKR1B10 expression and other clinical aspects like tumor size, lesions number, microvascular invasion, and metastasis is yet to be fully determined." (PMID 30125264, 2018).
tumor (continued). "In this project, we identified AKR1B10 functional as an oncogene in HCC through tumor/normal human tissue comparison from both GEO microarray and TCGA RNAseq dataset." (PMID 30038373, 2018). "AKR1B10 is overexpressed in neoplasms of various organs and systems, such as the lung, breast, gastrointestinal tract, pancreas, head, and neck." (PMID 30320113, 2018). "Tumor suppressing miR-383-5p was verified as the up-stream regulator modulating AKR1B10 expression in the process of HCC development." (PMID 30038373, 2018). "The AKR1B10 (aldo-keto reductase family 1 member B10) gene has important functions in carcinogen-induced neoplasia." (PMID 30320113, 2018). "Some of the studies also suggested the tumor suppressor effect of AKR1B10 and its clinical relevance." (PMID 30038373, 2018). "There are few reports on the participation of AKR1B10 in the development of non-neoplastic diseases." (PMID 30320113, 2018). "For the tumor samples, 69.81% (37/53) of the cases were observed highly expressed AKR1B10, and only a portion of 30.19% (16/53) cases presented low AKR1B10 expression." (PMID 30038373, 2018). "The findings above indicate that AKR1B10 functions to be a promotor inducing HeP3B cell growth in tumor process." (PMID 30038373, 2018). "Further experimental validations from three HCC cell lines (SMMC-7721, HePG2 and HeP3B) also suggested the ontogenetic functions of AKR1B10 in HCC tumor growth." (PMID 30038373, 2018). "Relative levels of AKR1B10 mRNA were higher in HCC tissues than in paired adjacent non-tumor tissues in 80.9% of patients." (PMID 28181486, 2017). "All the HCC tissues had higher level of AKR1B10 protein than their paired adjacent non-tumor tissues and both the two normal liver tissues showed low level of AKR1B10 protein." (PMID 28181486, 2017). "Detected by quantitative reverse transcription polymerase chain reaction, AKR1B10 mRNA expression showed significantly higher in HCC tissues than in adjacent non-tumor tissues, with a low level in normal liver tissues." (PMID 28181486, 2017). "But the relationship between AKR1B10 expression and early tumor recurrence in patients with HCC is uncertain." (PMID 28181486, 2017). "An possible explanation for this result is that tumor stage is a much stronger prognostic factor than AKR1B10 expression." (PMID 28181486, 2017). "Through statistically analyzing correlationships between AKR1B10 expression and clinicopathological parameters, we found the expression levels of AKR1B10 were highly positively correlated with tumor size and lymph node metastasis." (PMID 28402270, 2017). "Our results also suggest high AKR1B10 expression is a favorable factor for the OS of patients with HBV-related HCC, which is consistent with the result that high AKR1B10 expression negatively correlated with their early tumor recurrence." (PMID 28181486, 2017). "We found that AKR1B10 expression was increased in malignant tissues, which was correlated positively with tumor size, lymph node metastasis (p<0.05)." (PMID 28402270, 2017). "This study aimed to clarify the relationship between AKR1B10 expression and early tumor recurrence in patients with HBV-related HCC after liver resection." (PMID 28181486, 2017). "Aldo–keto reductase B10 (AKR1B10) is closely related to tumorigenesis and tumor development, and however, its expression level in NPC tissues is not clear." (PMID 26949513, 2016). "Apart from its physiological functions, a growing body of evidence indicates an important role of AKR1B10 in the development of various tumorous diseases." (PMID 27635343, 2016). "The log2 fold change of each of the “tumor-specific” genes identified in the manual curation for each setting/signature, indicated that AKR1B10 gene is the most upregulated, showing same levels in both “HCC-specific” and “HCV-HCC-specific” signatures." (PMID 27387388, 2016). "Secondly, IHC results confirmed that the protein level of AKR1B10 was higher in PHC tissues than peri-tumor tissues." (PMID 26948042, 2016).
tumor (continued). "A previous study revealed that inhibition of AKR1B10 results in apoptosis of tumor cells, in which cellular lipids, especially phospholipids, were decreased by over 50%14." (PMID 26948042, 2016). "Knockdown of AKR1B10 by siRNAs abolished 14-3-3ε-induced in vitro cell proliferation, anchorage-independent growth as well as in vivo tumor growth." (PMID 26516929, 2015). "The AKR1B10 mRNA and protein expression levels in 32 HCC tumor samples and correlations among the expression of AKR1B10 mRNA, protein levels and AKR1B10 copy number were investigated first." (PMID 24391771, 2013). "Since its identification in human hepatocellular carcinoma, AKR1B10 was shown to be differentially expressed in other tumor and normal tissues." (PMID 22876234, 2012). "Aldo‐keto reductase family 1 member B10 (AKR1B10) is involved in tumour metabolic reprogramming; however, its role in LR remains unclear." (PMID 41454479, 2026). "In addition, as a secretory protein pivotal in managing inflammatory signaling pathways, AKR1B10’s paracrine effects within the tumor microenvironment and its immunomodulatory roles in tumor progression warrant further elaboration." (PMID 40845116, 2025). "Enrichment analysis suggested that AKR1B10 might modulate inflammatory factors, which are crucial components of the tumor microenvironment and affect tumor growth and development." (PMID 38802416, 2024). "Furthermore, the relationship of AKR1B10 expression with clinicopathological features (age, gender, tumor size, staging, etc.)of HCC patients was analyzed using the TCGA database's LIHC dataset." (PMID 38802416, 2024). "Notably, the elevated AKR1B10 expression in OSCC tissues has been also observed and is associated with tumor recurrence and poor prognosis." (PMID 38671310, 2024). "AKR1B10 may play different roles within tumor cells and in the tumor microenvironment, and these roles may affect both tumor growth and patient prognosis." (PMID 39737179, 2024). "Additionally, CGA can target AKR1B10 and promote the polarization of TAMs towards an anti-tumor phenotype, enhancing T-cell cytotoxicity." (PMID 38931461, 2024). "Detailed mechanism analysis revealed a positive correlation between high AKR1B10 expression, immune cell infiltration, and pro-inflammatory cytokines, suggesting a potential DANCR-miR-216a-5p-AKR1B10 axis regulating the tumor microenvironment and impacting HCC development and prognosis." (PMID 38802416, 2024). "Importantly, increasing evidence has uncovered that AKR1B10 expression is elevated in OSCC tissues and associated with tumor recurrence and poor prognosis." (PMID 38671310, 2024). "Salvage experiments have suggested that AKR1B10 may act as a potential tumor suppressor in GC, inhibiting the migration, invasion, and adhesion of GC cells by modulating ITGA5 expression." (PMID 39737179, 2024). "Exploring the role of AKR1B10 in the immune microenvironment of GC is critical to determining whether AKR1B10 can become a potential target for tumor treatment." (PMID 37039038, 2023). "AKR1B10 was significantly reduced in tumor tissues and cells, and its overexpression could effectively inhibit tumor growth." (PMID 37751590, 2023). "The glycolysis ability of tumor cells with high-expressed AKR1B10 was reduced." (PMID 37884970, 2023). "The over-expression of AKR1B10 in early stages of well and moderately differentiated tumours, as well as its down-regulation in advanced tumour stages, demonstrated that AKR1B10 may be a useful marker for HCC differentiation." (PMID 36901717, 2023). "Depletion of AKR1B10 could facilitate tumor cell proliferation, resulting in tumor size progression and body weight gain in an in vivo xenograft model." (PMID 36661656, 2022). "In addition, AKR1B10 knockdown increased tumor cell proliferation, whereas its overexpression reduced tumor growth by enhancing EMT in an in vitro study." (PMID 36661656, 2022).
tumor (continued). "We analyzed the correlation of serum AKR1B10 with its expression in tumor tissues and tumor burden." (PMID 35280770, 2022). "Previous studies have shown that AKR1B10 may contribute to tumor progression through several mechanisms." (PMID 36661656, 2022). "The serum value of AKR1B10 was correlated with its expression in tumor tissues (right)." (PMID 35280770, 2022). "Growing evidence has shown that AKR1B10 is a tumor suppressor." (PMID 36661656, 2022). "Silencing of AKR1B10 also inhibited tumor proliferation in cell lines and animal studies." (PMID 36661656, 2022). "In addition, patient salivary levels of AKR1B10 are high and correlated with poor prognosis and elevated tumor recurrence incidence in OSCC." (PMID 34063865, 2021). "Then, we demonstrated that suppression of AKR1B10 by siRNA could reverse the tumor promoting effect induced by CBX7 knockdown on cell proliferation, invasion, and stemness." (PMID 34035231, 2021). "Furthermore, the expression of AKR1B10 was related to stage of tumor, that is, the expression level in tumor-node-metastasis (TNM) stage III–IV was lower than that in I–II." (PMID 34552036, 2021). "Finally, the radioresistance effect of AKR1B10 expression was evaluated by the tumor xenograft model of nude mice and the method of radiotherapy." (PMID 33767586, 2021). "An AKR1B10 inhibitor used widely in tumor treatment has recently attracted increased attention." (PMID 34552036, 2021). "Indeed, AKRB110 inhibited FGF1 in CRC cell lines, and elevated FGF1 in response to AKR1B10 depletion promoted xenograft tumor growth in a mouse model." (PMID 32615540, 2020). "Furthermore, cluster analysis indicated that both FGF1 and AKR1B10 expression levels were able to distinguish between the tumor and adjacent normal tissues, and pointed to a functional relationship as well." (PMID 32615540, 2020). "Furthermore, AKR1B10 expression was reduced in CRC tissues with tumor-node-metastasis (TNM) staging I-II compared to III-IV (P < 0.01)." (PMID 32615540, 2020). "Knockdown of AKR1B10 promoted tumor growth in vivo, and increased the expression of FGF1." (PMID 32615540, 2020). "We had validated highly expression of AKR1B10 in both HCC tumour cells and specimens." (PMID 32924268, 2020). "We identify the aldo-keto reductase AKR1B10 as a metastasis enhancer that has little impact on primary tumour growth or dissemination but promotes effective tumour growth in secondary sites and, in human disease, is associated with an increased risk of distant metastatic relapse." (PMID 31221959, 2019). "Reduced phospholipid levels concomitant with tumor cell apoptosis resulting from AKR1B10 inhibition indicate that the oncogenic function of AKR1B10 might be mediated by these molecules." (PMID 30959792, 2019). "EXC-15 (T08H10.1) has strong homology to aldo-keto-reductase family 1 member B10, a human intestinal protein that may detoxify aromatic aldehydes and ketones, and is overexpressed in tumor tissues." (PMID 30885922, 2019). "One explanation of this unusual expression pattern consists in tumor-induced reprogramming of the leukocytes' transcriptome 27, another - in tumor exosome-directed reprogramming of the gastrointestinal epithelium cells, where AKR1B10 is preferentially expressed." (PMID 31413744, 2019). "Knockdown of AKR1B10 negated IRAK1-induced tumor-initiating cells functions." (PMID 31598161, 2019).
tumor (continued). "Yet, such a relation with tumor grade has been a subject for several studies and a correlation between AKR1B10 expression and lower tumor stage has been found which may make AKR1B10 a possible marker for HCC differentiation level." (PMID 30125264, 2018). "Logically, degeneration of AKR1B10 in HCC cells could partly explain the tumor inhibiting mechanism that miR-383-5p induced in tumors." (PMID 30038373, 2018). "AKR1B10 expression could be a useful predictor for early tumor recurrence in patients with HBV-related HCC after liver resection." (PMID 28181486, 2017). "In addition, levels of AKR1B10 mRNA were significantly lower in normal liver tissues than in the adjacent non-tumor tissues (5.52 ± 1.37 vs 8.45 ± 2.78, P = 0.004)." (PMID 28181486, 2017). "After analyzing the correlation between AKR1B10 mRNA expression in PHC tissues and the clinical data, we found that AKR1B10 mRNA expression was associated with serum alpha-fetoprotein (AFP), tumor-node-metastasis (TNM) stage, and lymph node metastasis, but not with other clinicopathologic variables." (PMID 26948042, 2016). "In addition to AKR1B10 expression level, some clinical parameters like gender, tumor size, tumor number, TNM stage, and portal vein tumor thrombus (PVTT) were associated with DFS." (PMID 26948042, 2016). "Additionally, an in vivo study was performed to elucidate the effect of 14-3-3ε/AKR1B10 expression on HCC tumor growth." (PMID 26516929, 2015). "Given these facts, we thus hypothesized that 14-3-3ε-induced AKR1B10 may promote HCC tumor growth via regulation of RA production." (PMID 26516929, 2015). "AKR1B10 can therefore be thought of as playing dual roles during tumor progression of HCC." (PMID 26516929, 2015). "Silencing of AKR1B10 with siRNA suppresses HCC tumor growth." (PMID 26516929, 2015). "The role of AKR1B10 during HCC tumor prognosis is paradoxical." (PMID 26516929, 2015). "However, silencing of AKR1B10 expression in 14-3-3ε overexpressing cells resulted in an increase in the levels of retinoic acid in the tumor-bearing mice, which was significantly correlated with reduction of tumor size." (PMID 26516929, 2015). "It is therefore a reasonable speculation that AKR1B10 contributes to tumor growth by reducing RA production and regulating lipid metabolism." (PMID 26516929, 2015). "Furthermore, AKR1B10 silencing increased retinoic acid (RA) levels in the serum of tumor-bearing mice and RA treatment attenuated 14-3-3ε-induced HCC cell proliferation." (PMID 26516929, 2015). "AKR1B10 may synergize with other regulators to play paradoxical roles in regulating HCC tumor growth, EMT and metastasis." (PMID 26516929, 2015). "Meanwhile, AKR1B10 may play different roles at different stages of tumor development." (PMID 39737179, 2024). "Moreover, patient populations differ in terms of tumor stage, treatment modality, and genetic background, and these factors may collectively influence the relationship between AKR1B10 expression and prognosis." (PMID 39737179, 2024). "This may be closely related to AKR1B10’s aldose reductase activity, whose protumorigenic effects are attenuated upon inhibition of the inflammatory factors IL-1α and IL-6, thereby inhibiting tumor cell growth." (PMID 39737179, 2024). "The expression of AKR1B10 may also vary across different sites and stages of the same tumor." (PMID 39737179, 2024). "Notably, knockdown of AKR1B10 rescued the tumor-promoting effects induced by METTL3 overexpression." (PMID 36476503, 2022). "In addition, targeting against AKR1B10 and inducing autophagy of tumor cells may effectively inhibit the growth of tumor cells." (PMID 34552036, 2021). "Therefore, AKR1B10 may play a major role in the IR resistance by enhancing DNA repair ability of radioresistant tumor cells." (PMID 33767586, 2021). "In addition to tumor progression, changes in AKR1B10 expression levels are associated with several noncanceraous diseases and chemoresistance (as described later)." (PMID 34063865, 2021).